COPRS (coordinator of PRMT5 and differentiation stimulator)
Description:
Histone-binding protein required for histone H4 methyltransferase activity of PRMT5. Specifically required for histone H4 'Arg-3' methylation mediated by PRMT5, but not histone H3 'Arg-8' methylation, suggesting that it modulates the substrate specificity of PRMT5. Specifically interacts with the N-terminus of histone H4 but not with histone H3, suggesting that it acts by promoting the association between histone H4 and PRMT5. Involved in CCNE1 promoter repression. Plays a role in muscle cell differentiation by modulating the recruitment of PRMT5 to the promoter of genes involved in the coordination between cell cycle exit and muscle differentiation (By similarity).
Synonyms: C17orf79; COPR5; TTP1; HSA272196
Tractability: Antibody: its Gene Ontology location is reachable by antibodies, with high confidence. PROTAC: its protein half-life has been measured.
Gene: Protein-coding gene on chromosome 17 (31,851,871 to 31,859,291, reverse strand). Ensembl gene ENSG00000172301.
Subcellular location: Nucleus
Subcellular location (Human Protein Atlas): Nucleoplasm; Cytosol; Plasma membrane
Pathways (Reactome):
Chromatin organization: RMTs methylate histone arginines
Gene Ontology:
Molecular function: histone binding; protein binding
Biological process: chromatin remodeling; muscle organ development; positive regulation of rRNA processing
Cellular component: methylosome; nucleoplasm; nucleus
Genetic constraint (gnomAD): Loss-of-function variants: 8 observed, 14.82 expected, observed/expected ratio (o/e) 0.54, 90% interval 0.32 to 0.97. The upper end of that interval is the gene's LOEUF score, 0.97, which puts it in group 4 of 6, group 1 being the genes least tolerant of losing a copy. Missense variants: 199 observed, 191.13 expected, observed/expected ratio (o/e) 1.04, 90% interval 0.93 to 1.17. Synonymous variants: 71 observed, 71.38 expected, observed/expected ratio (o/e) 0.99, 90% interval 0.82 to 1.21.
Homologues: Orthologues: chimpanzee COPRS (99% identical), macaque COPRS (93% identical), pig COPRS (82% identical), dog COPRS (79% identical), mouse Coprs (72% identical), guinea pig COPRS (72% identical), rat Coprs (64% identical), rabbit COPRS (61% identical).
Diseases named in the same sentence as COPRS in open-access papers:
COPRS is named in the same sentence as 3 diseases in open-access papers, as found by Europe PMC text mining. Sharing a sentence is not in itself a finding about the gene and the disease. The quoted sentences say what the papers report.
tumor (3 papers, 2017 to 2024). "In addition to the deletion of SUZ12 and ATAD5, hemizygosity forthe genes COPRS, UTP6 and RNF135 may alsocontribute to the increased tumour risk associated with NF1 microdeletions." (PMID 28213670, 2017). "Thus, the analysis of COPRS expression should be performed using primary MPNST samples(with high proportions of tumour cells) from patients with NF1 microdeletions to explore the role of COPRS during MPNST development or progression inNF1 microdeletion patients." (PMID 28213670, 2017).
COPRS also shares sentences with these, for which no sentence is quoted: Cognitive impairment (1 paper); intellectual disabilities (1).